ATIC (5-aminoimidazole-4-carboxamide ribonucleotide formyltransferase/IMP cyclohydrolase)
Description:
Bifunctional enzyme that catalyzes the last two steps of purine biosynthesis. Acts as a transformylase that incorporates a formyl group to the AMP analog AICAR (5-amino-1-(5-phospho-beta-D-ribosyl)imidazole-4-carboxamide) to produce the intermediate formyl-AICAR (FAICAR). Can use both 10-formyldihydrofolate and 10-formyltetrahydrofolate as the formyl donor in this reaction. Also catalyzes the cyclization of FAICAR to inosine monophosphate (IMP). Is able to convert thio-AICAR to 6-mercaptopurine ribonucleotide, an inhibitor of purine biosynthesis used in the treatment of human leukemias. Promotes insulin receptor/INSR autophosphorylation and is involved in INSR internalization.
Synonyms: PURH; AICARFT; IMPCHASE; AICAR; HEL-S-70p
Tractability: Small molecule: a structure with a bound ligand is known; a high-quality ligand is known; it has a high-quality binding pocket; it belongs to a druggable protein family. Antibody: its Gene Ontology location is reachable by antibodies, with high confidence; the Human Protein Atlas places it where antibodies can reach. PROTAC: ubiquitination databases record sites on it; its protein half-life has been measured; a small molecule that binds it is known.
Target class: Enzyme
Chemical probes: LSN-3213128 (high quality)
Safety:
Unwanted effects reported when the protein is acted on. In parentheses: how it was acted on, where the effect was seen, and who reports it.
discontinue treatment due to toxicity (source: ClinPGx)
Gene: Protein-coding gene on chromosome 2 (215,311,956 to 215,349,773, forward strand). Ensembl gene ENSG00000138363.
Subcellular location: Cytoplasm, cytosol
Subcellular location (Human Protein Atlas): Cytosol; Plasma membrane
Pathways (Reactome):
Disease: Signaling by ALK fusions and activated point mutants
Metabolism: Purine ribonucleoside monophosphate biosynthesis
Gene Ontology:
Molecular function: cadherin binding; IMP cyclohydrolase activity; phosphoribosylaminoimidazolecarboxamide formyltransferase activity; protein homodimerization activity
Biological process: 'de novo' AMP biosynthetic process; 'de novo' IMP biosynthetic process; 'de novo' XMP biosynthetic process; GMP biosynthetic process; nucleobase-containing compound metabolic process; animal organ regeneration; brainstem development; cerebellum development; cerebral cortex development; dihydrofolate metabolic process; purine nucleotide biosynthetic process; tetrahydrofolate biosynthetic process
Cellular component: extracellular exosome; membrane; cytosol
Genetic constraint (gnomAD): Loss-of-function variants: 58 observed, 69.14 expected, observed/expected ratio (o/e) 0.84, 90% interval 0.68 to 1.04. The upper end of that interval is the gene's LOEUF score, 1.04, which puts it in group 4 of 6, group 1 being the genes least tolerant of losing a copy. Missense variants: 760 observed, 740.1 expected, observed/expected ratio (o/e) 1.03, 90% interval 0.97 to 1.09. Synonymous variants: 271 observed, 274.02 expected, observed/expected ratio (o/e) 0.99, 90% interval 0.89 to 1.09.
Homologues: Orthologues: chimpanzee ATIC (99% identical), macaque ATIC (98% identical), dog ATIC (95% identical), rabbit ATIC (94% identical), pig ATIC (93% identical), rat Atic (91% identical), mouse Atic (91% identical), guinea pig ATIC (82% identical), zebrafish atic (79% identical), tropical clawed frog atic (78% identical), Drosophila melanogaster CG11089 (71% identical), Caenorhabditis elegans atic-1 (60% identical).
Diseases named in the same sentence as ATIC in open-access papers:
ATIC is named in the same sentence as 67 diseases in open-access papers, as found by Europe PMC text mining. Sharing a sentence is not in itself a finding about the gene and the disease. The quoted sentences say what the papers report.
hepatocellular carcinoma (13 papers, 2017 to 2024). A malignant tumor that arises from hepatocytes. "Abnormal ATIC, as the host gene of circ-ATIC, has also been implicated in the development of many types of cancer such as hepatocellular cancer, multiple myeloma tissues, and lung adenocarcinoma." (PMID 39056681, 2024). "ATIC inhibits autophagy and promotes proliferation, invasion, and metastasis of hepatocellular carcinoma cells through the AKT/FOXO3 signaling pathway." (PMID 38625586, 2024). "The overexpression of ATIC and RHEB was associated with metastasis and poor prognosis in hepatocellular carcinoma." (PMID 35573678, 2022). "ATIC overexpression in hepatocellular carcinoma cells enhances their proliferation." (PMID 36557247, 2022). "Moreover, ATIC can also be used as a prognostic biomarker for hepatocellular carcinoma." (PMID 36860325, 2023). "A recent study also showed that ATIC is upregulated in Hepatocellular carcinoma (HCC) tissues, and high levels of ATIC are correlated with poor survival in HCC patients." (PMID 35056904, 2021). "In prediction models for autophagy-related genes, multiple autophagy genes are involved, such as ATG10, ATIC, BIRC5, and CAPN10, and their changes effectively affect the survival time of hepatocellular carcinoma patients." (PMID 39502521, 2024).
rheumatoid arthritis (10 papers, 2009 to 2026). A chronic, systemic autoimmune disorder characterized by inflammation in the synovial membranes and articular surfaces. "Two variants in ATIC (rs4673993, T allele) and SLC19A1 (rs1051266, C allele), which impact methotrexate (MTX) efficacy in rheumatoid arthritis, demonstrated high prevalence among the enrolled Saudis with allele frequencies of 71% and 48%, respectively." (PMID 40376268, 2025). "Importantly, CellAwareGNN prioritizes promising repurposing candidates, including Ocrelizumab for Pemphigus via CD20-expressing B cells, Methotrexate for Pemphigus through DHFR and ATIC activity in T and B cells, and Rosiglitazone for Rheumatoid Arthritis through PPAR- γ activation." (PMID 42124589, 2026).
breast carcinoma (8 papers, 2016 to 2023). "Importantly, in HER2-positive breast cancer, decreased expression of metabolism-related genes ATIC, HPRT1, ASNS, SULT1A2, and HAL was associated with increased survival." (PMID 35663326, 2022). "The small-molecule inhibitor of ATIC has been shown to suppress the proliferation of breast cancer cells." (PMID 31552180, 2019). "ATIC (aminoimidazole carboxamide ribonucleotide transformylase/inosine monophosphate cyclohydrolase), required for de novo purine biosynthesis, is important in cell proliferation and an inhibitor of its dimerization was inhibitory to breast cancer cell growth." (PMID 31139569, 2019). "Cpd14 is a small-molecule inhibitor that prevents the homodimerization and activation of ATIC and thereby inhibits the proliferation of MCF-7 breast cancer cells and HCT116 cells." (PMID 36750554, 2023). "Compared with normal control tissues, the expression of HPRT1, ASNS, ATIC, SULT1A2, and HAL was significantly increased in HER2-positive breast cancer samples." (PMID 35663326, 2022). "Considering that the experiments were performed using triple-negative breast cancer, but based on the correlations we observed between the expression of ATIC and the survival outcome of HER2-positive breast cancer, the targeted ATIC products may be more toxic to HER2-positive breast cancer." (PMID 35663326, 2022). "MTX caused a strong increase (~30 fold) in endogenous AICAR levels in breast cancer cells and mouse embryonic fibroblasts (MEFs), with little effect on the downstream metabolites IMP and AMP, suggesting a blockage in de novo purine biosynthesis at the ATIC step." (PMID 32398698, 2020). "In addition, ATIC, HPRT1, ASNS, SULT1A2, and HAL may represent attractive therapeutic targets for HER2-positive breast cancer, and require further validation studies, especially considering that treatment with specific inhibitors may alter the expression of these metabolic genes." (PMID 35663326, 2022).
liver cancer (6 papers, 2020 to 2025). An epithelial or non-epithelial malignant neoplasm that arises from the liver. "High levels of ATIC-associated aggressive liver cancer pathology will lead to a poor prognosis in terms of patient survival." (PMID 34803509, 2021). "A comprehensive in vitro and in vivo study demonstrated that ATIC facilitates the development of liver cancer via the AKT/FOXO3 pathway." (PMID 39001904, 2024). "A subsequent multivariate survival analysis identified five key prognostic ARGs (ATIC, BAX, BIRC5, CAPNS1, and FKBP1A) that were used to construct prognostic risk models, which provided an accurate prognosis for patients with malignant liver tumors." (PMID 35402224, 2022). "ATIC was confirmed to inhibit autophagy and promote the proliferation, invasion and metastasis of liver cancer cells through the AKT/Forkhead box subgroup O3 (FOXO3) signaling pathway in vitro and in vivo." (PMID 34803509, 2021). "In the analysis of the correlation between ATIC expression and the clinicopathological characteristics of patients with liver cancer, we found that ATIC expression is related to lymph node invasion and patient prognosis." (PMID 34803509, 2021). "The western blot results were consistent with the PCR results, showing that ATIC was expressed at high levels in liver cancer tissues and liver cancer cell lines." (PMID 34803509, 2021). "ATIC inhibits autophagy and promotes the progression of liver cancer through the AKT/FOXO3 signaling pathway." (PMID 34803509, 2021). "The multivariate Cox regression analysis further confirmed that ATIC expression was significantly correlated with the prognosis of patients with liver cancer (P=0.006)." (PMID 34803509, 2021). "We found that ATIC inhibited autophagy and promoted liver cancer progression by modulating the AKT/Forkhead box subgroup O3 (FOXO3) pathway." (PMID 34803509, 2021). "The results of the Cox regression analysis showed that, compared with patients with liver cancer in the low ATIC expression group, high ATIC expression was closely related to a poor prognosis of patients with liver cancer (P=0.002)." (PMID 34803509, 2021). "We verified that the key gene ATIC affects tumor progression by modulating autophagy in vitro and in vivo, and the effect of ATIC on autophagy in liver cancer has been clarified here for the first time." (PMID 34803509, 2021). "In this study, we proved through in vivo and in vitro experiments that ATIC promotes the progression of liver cancer through the AKT/FOXO3 pathway." (PMID 34803509, 2021). "In this study, we have identified an anti-ATIC autoantibody as a novel autoantibody biomarker for liver cancer." (PMID 33352757, 2020). "The bifunctional enzyme ATIC can promote the proliferation of liver cancer." (PMID 36860325, 2023). "We collected tumor samples and paracancerous samples from 52 patients with liver cancer from the Biological Repositories, Zhongnan Hospital of Wuhan University and verified that ATIC was expressed at significantly higher levels in liver cancer tissue samples (P<0.001)." (PMID 34803509, 2021). "Furthermore, we have suggested that ATIC inhibits autophagy and promotes liver cancer progression through the AKT/FOXO3 pathway." (PMID 34803509, 2021). "Liver cancer cells were transfected with shRNA NC and the ATIC shRNA." (PMID 34803509, 2021). "More importantly, ATIC was suggested as a poor prognosis marker of liver cancer." (PMID 33352757, 2020). "The results from TCGA database indicated that overexpression of ATIC, BIRC5, BAX, CAPNS1, and FKBP1A was closely related to an inferior OS of patients with liver cancer." (PMID 35402224, 2022). "The expression of ATIC, HDAC1, RHEB, SPNS1 and TMEM74 in liver cancer tissues was significantly higher than that in normal liver tissues." (PMID 34803509, 2021).
lung carcinoma (6 papers, 2010 to 2022). "According to recent studies, ATIC is expressed at high levels in lung cancer and is related to a poor patient prognosis." (PMID 35402224, 2022). "GENT analysis also showed that ATIC expression is elevated in various extrahepatic tumors, including colon and lung cancer." (PMID 33352757, 2020). "Recent bioinformatics studies using TCGA dataset concurred that ATIC as one of the autophagy-related genes was associated with increased cancer risks of HCC and lung cancer." (PMID 33520699, 2020).
anaplastic large cell lymphoma (3 papers, 2013 to 2016). Anaplastic large cell lymphoma (ALCL) is a rare and aggressive peripheral T-cell non-Hodgkin lymphoma, belonging to the group of CD30-positive lymphoproliferative disorders, which affects lymph nodes and extranodal sites. "ATIC-ALK fusion mutations are very rare, comprising approximately 1% of ALK-fusion mutations in anaplastic large cell lymphomas (ALCL)." (PMID 27846861, 2016). "Many translocations have been found with this ALK gene, including EML4:ALK which is responsible for approximately 3-5% of non-small-cell lung cancer(NSCLC), RANBP2:ALK, TPM4:ALK in inflammatory myofibroblastic tumor, NPM1:ALK, ATIC:ALK, TFG:ALK in anaplastic large cell lymphoma, and so on." (PMID 24564548, 2013).
colon cancer (3 papers, 2020 to 2025). "Association between SUCLG2P2, SUCLG2 and ATIC genes and clinicopathological parameters of colon cancer patients." (PMID 34589110, 2021). "The pseudogene SUCLG2P2 along with two other genes (SUCLG2 and ATIC) were introduced as potential prognostic markers for colon cancer, aiding in predicting patient outcomes and tailoring treatment strategies." (PMID 40556338, 2025). "In conclusion, the expressions of SUCLG2P2, SUCLG2 and ATIC in colon cancer and normal tissues were different, and they were related to survival." (PMID 34589110, 2021). "The expression of SUCLG2P2 was also low in colon cancer, but the expression of ATIC was high in most tumors, including colon cancer." (PMID 34589110, 2021).
colorectal cancer (3 papers, 2022 to 2023). A primary or metastatic malignant neoplasm that affects the colon or rectum. "This acetylation step, mediated by lysine acetyltransferase 2B (KAT2B), occurs at ATIC Lys 266, dramatically inhibits ATIC activity, and inversely correlates with colorectal cancer (CRC) tumor growth in vitro and in vivo, and acetylation of ATIC is downregulated in human CRC samples." (PMID 36750554, 2023). "When colorectal cancer was compared with the pool of controls and inflammatory bowel disease, the most significant signal in CRC vs controls (upstream of the ABCA12 and ATIC genes) was detected." (PMID 36077729, 2022).
lymphoma (3 papers, 2020 to 2022). A malignant (clonal) proliferation of B- lymphocytes or T- lymphocytes which involves the lymph nodes, bone marrow and/or extranodal sites. "In addition, the ATIC gene is associated with the risk of lymphoma progression in cases of ATIC protein fusion with the protein of oncogene ALK (anaplastic lymphoma kinase)." (PMID 35205374, 2022). "The fused protein between ATIC and anaplasia lymphoma kinase (ALK, a common oncogene) was discovered in lymphoma patients." (PMID 34650911, 2021). "Importantly, fusion proteins of ATIC and anaplastic lymphoma kinase (ALK, a common oncogene) were frequently found in lymphoma patients." (PMID 33520699, 2020).
AICA-ribosiduria (2 papers, 2022). AICA-ribosiduria is an extremely severe inborn error of purine biosynthesis characterized clinically in the single reported case to date by profound intellectual deficit, epilepsy, dysmorphic features of the knees, elbows, and shoulders and congenital blindness. "AICA-ribosiduria (ATIC deficiency, OMIM 608688) is caused by mutations in the ATIC gene encoding for AICARTF (AICAR transformylase) and IMPCH, which catalyzes the last two reactions of PDNS." (PMID 35323684, 2022). "The ADSL reverse reaction is highly activated in ATIC KO cells that naturally accumulate AICAR, and most probably also in the cells of AICAribosiduria patients." (PMID 36557247, 2022).
cholangiocarcinoma (2 papers, 2021 to 2022). A carcinoma that arises from the intrahepatic biliary tree (intrahepatic cholangiocarcinoma) or from the junction, or adjacent to the junction, of the right and left hepatic ducts (hilar cholangiocarcinoma). "In research on nucleotide anabolism in cholangiocarcinoma, CDC like kinase 3 (CLK3) was found to activate the rate-limiting enzyme in de novo purine anabolism, ATIC, by regulating the USP13/Fbxl14/c-Myc signaling axis, thereby promoting the molecular progression of cholangiocarcinoma." (PMID 33952722, 2021).
glioblastoma (2 papers, 2023 to 2024). The most malignant astrocytic tumor (WHO grade IV). "Moreover, inhibition of ATIC not only impairs de novo purine biosynthesis but also leads to a large accumulation of AICAR, which potently activates AMPK and inhibits the growth of some glioblastomas by repressing adipogenesis." (PMID 36750554, 2023).
Juvenile Arthritis (2 papers, 2015 to 2020). "In our analysis, the most common functional variants of ATIC, ITPA, and SLC19A1 were associated with clinical response to methotrexate evaluated as remission stable for a 6-months period, as ACRPed score and as change in Juvenile Arthritis Disease Score (JADAS) in 69 patients with JIA." (PMID 25852556, 2015).
metabolic syndrome (2 papers, 2023 to 2024). A cluster of metabolic risk factors for CARDIOVASCULAR DISEASES and TYPE 2 DIABETES MELLITUS. "A dipeptide that blocks the requisite dimerization of ATIC (AICAR Transformylase/Inosine Monophosphate Cyclohydrolase) has been previously shown to activate the AMPK signaling pathway and ameliorate the metabolic syndrome in mice." (PMID 39043420, 2024). "Interestingly, however, moderately reducing ATIC activity in adult mice with a specific inhibitor is beneficial, leading to an increase in AICAR and AMP-activated kinase (AMPK) activity, ameliorating metabolic syndrome phenotypes." (PMID 36627750, 2023).
neuroblastoma (2 papers, 2019 to 2021). Neuroblastoma (NB) is the most common solid, extracranial childhood tumor. "Besides, one carbon pool by folate was also identified to be associated with MNA neuroblastoma, which generated formates, the precursor to 10-formyltetrahydrofolate in the mitochondria and exported into cytosol for the need of transformylase enzymes, GRAT and ATIC in purine biosynthesis." (PMID 31624245, 2019).
non-small cell lung carcinoma (2 papers, 2017 to 2022). A group of at least three distinct histological types of lung cancer, including non-small cell squamous cell carcinoma, adenocarcinoma, and large cell carcinoma. "Recent study demonstrates that inhibition AICART activity of ATIC and a subsequent rise in intracellular 5-Aminoimidazole-4-carboxamide ribonucleotide (ZMP) plays a significant role in the anti-tumorigenic effects of the drug pemetrexed, which is used against non-small cell lung cancer." (PMID 29246230, 2017).
psoriasis (2 papers, 2009 to 2023). An autoimmune condition characterized by red, well-delineated plaques with silvery scales that are usually on the extensor surfaces and scalp. "We conclude that genetic variation across the genes FPGS, GGH, MTHFR and ATIC is not predictive of either efficacy or toxicity of methotrexate in patients with psoriasis." (PMID 19016697, 2009).
triple-negative breast carcinoma (2 papers, 2020 to 2022). An invasive breast carcinoma which is negative for expression of estrogen receptor (ER), progesterone receptor (PR), and human epidermal growth factor receptor 2 (HER2). "Small molecule inhibitors, LSN3213128 and 326203-A, which target 5-aminoimidazole-4-carboxamide ribonucleotide formyltransferase (AICARFT), a subunit of the ATIC enzyme, are being evaluated for treatment of triple-negative breast cancer." (PMID 32218208, 2020).
arterial disease (1 paper, 2024). "Moreover, ATIC‐associated de novo purine synthesis is critically involved in arterial disease." (PMID 39350574, 2024).